INS (insulin)
Diseases named in the same sentence as INS in open-access papers (continued):
Sharing a sentence is not in itself a finding about the gene and the disease.
diabetes (continued). "Signs of autoimmune abnormalities such as insulin autoantibody (IAA), islet cell antibody (ICA), and glutamic acid decarboxylase antibody (GADA) predicted rapid progression to insulin-requiring diabetes." (PMID 29887833, 2018). "In an animal model of diabetes, the SIRT1 is expressed in pancreatic β-cells to enhance insulin secretion in response to glucose." (PMID 30246793, 2018). "Specifically, treatment with a pan-Hsp90 inhibitor was shown to improve glucose homeostasis and insulin sensitivity in db/db and diet-induced obese (DIO) mouse models of diabetes, respectively." (PMID 29434648, 2018). "Pioglitazone was originally designed as an anti-diabetic drug due to its insulin sensitizing effect and was approved by the FDA and widely used clinically to treat type 2 diabetes mellitus with few side effects." (PMID 29791472, 2018). "Distinct characteristic modulations of the enzymatic conversions catalyzed by LDH and ALT were detected in HP [1-13C]pyruvate MR spectra of gluconeogenic tissues of Zucker rat models of type 1 (insulin-deprived STZ-treated wild type) and type 2 (ZDF) diabetes." (PMID 29391429, 2018). "Indices describing glucose homeostasis included fasting plasma glucose (FPG), fasting insulin, glycated hemoglobin (HbA1c), the homeostatic model assessment 2-insulin resistance (HOMA2-IR) and odds of pre-diabetes." (PMID 29739382, 2018). "Insulin-treated T2DM patients with poor glycemic control should be screened for comorbid depression and provided with suitable interventions for optimized diabetes management." (PMID 29508275, 2018). "Among participants with previously diagnosed diabetes, IFG, and NFG, insulin and HOMA-IR levels were higher in females than in males (P < 0.001)." (PMID 30211231, 2018). "Due to the close relationship to insulin, the system of IGF and its binding proteins has been first explored as biomarkers in diabetes, especially T1DM." (PMID 30214426, 2018). "After adjustment for systolic BP, duration of diabetes, eGFR, HbA1c, triglycerides, RAAS blockers, antiplatelet agents, statins and insulin use, the differences in MFR between groups of albuminuria remained significant." (PMID 29325551, 2018). "In animal models of diabetes, inhibition of GRK2 and GRK3 through these synthetic peptides rescues glucose tolerance and enhances insulin sensitivity." (PMID 30538631, 2018). "There are three main types of diabetes: type 1 diabetes (insulin dependent), T2DM (insulin resistance or insulin insensitivity) and gestational diabetes." (PMID 30060458, 2018). "The diabetes attitudes, wishes, and needs (DAWN) study also evaluated patient attitudes towards insulin therapy." (PMID 30116737, 2018). "Type 2 diabetes mellitus (T2DM) is a multifactorial and genetically heterogeneous disease which is characterized by insulin hypo-secretion and/or insulin resistance (IR)." (PMID 29433562, 2018). "Insulin resistance in AD and diabetes can lead to hyperinsulinemia, thereby, saturating IDE for insulin and Aβ degradation." (PMID 30542257, 2018). "Duration of diabetes, years taking insulin, TDD insulin and mean HbA1c were similar in Brazil, Latin America, and worldwide." (PMID 30498521, 2018). "Type 2 diabetes mellitus (T2DM), characterized by increased blood glucose level resulting from disturbances of insulin secretion, insulin action or both, is a complex disorder influenced by both lifestyle and genetic factors." (PMID 30453687, 2018). "A significant increase was observed in parameters involved in diabetes such as FBS (p = 0.01), insulin (p = 0.04) and HOMA-IR (p = 0.04) in the case group compared to the control group." (PMID 29932432, 2018). "The rapid-acting insulin analogues (RAIAs) aspart and lispro have been approved for use in CSII therapy in patients with diabetes." (PMID 29780415, 2018).
diabetes (continued). "Because of these shared features between AD and diabetes, AD has also been referred to as type III diabetes mellitus, leading to a growing interest in using insulin sensitizing agents as a potential therapy for AD." (PMID 30420872, 2018). "Type 2 diabetes mellitus (T2DM), which is characterized by peripheral insulin resistance and impaired insulin secretion, is a chronic metabolic disease that has shown an increased incidence in obese and aged individuals in recent years." (PMID 29682407, 2018). "Type 2 diabetes mellitus (T2DM) is a metabolic disorder that is characterized by functional defects in glucose metabolism and insulin secretion." (PMID 29770126, 2018). "Similarly, the two strongest weighted loci in Cluster 2 are ARAP1, a locus at which diabetes risk is thought to be mediated by modulation of STARD10 expression in pancreatic beta cells, and SPRY2, a locus at which the closest gene, SPRY2, regulates insulin transcription." (PMID 30240442, 2018). "Thus, targeting brain insulin signaling through the administration of drugs that have already been previously approved for the treatment of diabetes mellitus, such as insulin and drugs that improve insulin sensitivity, could expedite their development for the treatment of AD." (PMID 29467605, 2018). "On discharge, 27% of the diabetes group were taking metformin, 31% were taking a sulphonylurea, 7% were on a DPP-4 inhibitor and 36% were prescribed insulin." (PMID 30202020, 2018). "The Diabetes Control and Complications Trial (DCCT) identified weight gain as an adverse consequence of intensive insulin therapy." (PMID 29549246, 2018). "Diabetes mellitus (DM) is a syndrome characterized by chronic hyperglycemia and disorders of fat and protein metabolisms due to an insufficient secretion or impaired action of insulin." (PMID 30320140, 2018). "Diabetes patients are responsible for their daily care, such as self-monitoring blood glucose (SMBG), diet management, and insulin dose adjustments." (PMID 29854822, 2018). "In addition, the measurement of the LMW/total ratio in diabetic subjects may be useful for evaluating the etiology of their diabetes and for selecting an appropriate therapy (e.g., insulin-sensitizing drugs for diabetic subjects with a relatively high LMW/total ratio)." (PMID 29494595, 2018). "Patients with diabetes who abuse substances may have poorer glycaemic control due to a number of reasons including their poor nutrition state, mental illness and erratic lifestyle such as poor compliance with prescribed medications including insulin and poor diabetic clinic attendance." (PMID 30501025, 2018). "Selected diabetes-related autoantibodies such as GAD-ab, IA2-ab, ZnT8-ab were tested before the initiation of insulin therapy." (PMID 29327148, 2018). "In this review, we discuss the effects of obesity and diabetes-induced inflammation on the BBB, the roles played by leptin and insulin resistance, as well as BBB changes occurring at the molecular level." (PMID 30618559, 2018). "For diabetes study, there is a high correlation between magnesium and chloride; free triiodothyronine and LDLC; and c-peptide of insulin and insulin." (PMID 29650030, 2018). "Plasma level of insulin decreased in mice administered with diabetic SLN containing myricitrin 1, 3, and 10 mg/kg when compared to the diabetes + metformin group (p < 0.01, p < 0.01, and p < 0.05, resp)." (PMID 30116491, 2018). "In diabetes, activation of the pancreatic RAS by hyperglycaemia and hyperlipidaemia can result in reduced insulin biosynthesis, insulin secretion, and islet blood flow, and also increased β-cell apoptosis, oxidative stress, and islet fibrosis." (PMID 30622676, 2018). "The main outcome measures were: HbA1c, fasting glucose, BMI, waist circumference, daily insulin dose, hypoglycemic events, and analysis of QOL through the Diabetes-Specific Quality-of-life Scale, which evaluates individual treatment goals in patients with DM1." (PMID 29791661, 2018).
diabetes (continued). "For the 81 patients included in the study, 46 (57%) were male, median age at diabetes diagnosis was 8·0 weeks (IQR 4·0–12·0; n=74), and median age at transfer from insulin to sulfonylureas was 4·8 years (1·7–11·4; n=81)." (PMID 29880308, 2018). "Type 2 diabetes mellitus (T2DM) is characterized by dysregulation of carbohydrate, lipid, and protein metabolism, and results from impaired insulin secretion, insulin resistance, or a combination of both." (PMID 30249015, 2018). "Fasting adiponectin, insulin, glucose, and HbA1c were determined in 376 patients with known T2DM and 575 subjects with undiagnosed diabetes but with family history of T2DM." (PMID 30069271, 2018). "Recently, the endogenous fatty acid palmitic acid-5-hydroxystearic acid (5-PAHSA) was found to increase insulin sensitivity and have anti-inflammatory effects in mice with high-fat diet (HFD)-induced diabetes." (PMID 30666198, 2018). "Increases in postmeal insulin may be undesirable, as postprandial hyperinsulinemia has been found to be independently associated with coronary artery disease risk among women without diabetes." (PMID 30126094, 2018). "A principal challenge of intensive diabetes care is maintaining frequent self-monitoring of blood glucose (SMBG) and insulin dosing." (PMID 33052121, 2018). "In the present study, GEE reversed the diabetes-induced downregulation of p-IRS, p-PI3K, and p-Akt in peripheral tissues, indicating that GEE restores insulin signaling in db/db mice." (PMID 29316644, 2018). "Type 2 diabetes mellitus (T2DM) is characterized by a sustained decrease in the insulin secretion of pancreatic β-cells, which leads to insufficient insulin to fulfill the requirement of the body." (PMID 30687277, 2018). "Diabetes Mellitus Type 2 (DMT2) is a metabolic disease characterized by chronically elevated levels of blood glucose, due to impaired insulin secretion and insulin resistance." (PMID 29342984, 2018). "On the other hand, few studies have demonstrated that atorvastatin did not worsen insulin sensitivity in patients with diabetes, whereas one study suggested that patients treated with atorvastatin may be at a lower risk of developing new onset diabetes." (PMID 30425742, 2018). "BACE1 inhibition restores functional cell-surface IR and increases insulin signaling, supporting the use of BACE1 inhibitors to improve liver insulin signaling during diabetes." (PMID 29610518, 2018). "Hypoglycemia affects patient safety and glycemic control during insulin treatment of both type 1 (T1DM) and type 2 diabetes mellitus (T2DM)." (PMID 30479669, 2018). "Insulin resistance (IR) is a major defect in type 2 diabetes mellitus (T2DM), referring to the reduced sensitivity of the target tissues in response to insulin." (PMID 29721029, 2018). "The levels of insulin and HOMA-IR were higher in females than in males among the participants with previously diagnosed diabetes, IFG, and NFG and decreased with age for IFG and NFG participants." (PMID 30211231, 2018). "As expected, the levels of fasting glucose, HbA1c, fasting serum insulin and HOMA-IR were markedly elevated in these diabetes patients." (PMID 29540751, 2018). "For nonresponders to IGlar who have reached FBG target or whose up-titration of IGlar dose is limited by the frequency and/or severity of hypoglycemia, diabetes treatment should be intensified with PPG-lowering agents, such as prandial insulin or GLP1-RA." (PMID 29760944, 2018). "Previous studies that explored SIRT1 in diabetes have focussed on type 2 diabetes, showing that SIRT1 activation enhances ß-cell function, improves insulin sensitivity and increases ß cell mass to attenuate hyperglycaemia." (PMID 30228292, 2018). "The reduction in insulin release and liver glycogen level of diabetic control group rats are due to STZ (a known diabetogen) used for induction of diabetes in rats that brings about the destruction of β- cells of the islets of Langerhans." (PMID 29890969, 2018).
diabetes (continued). "This increase in PTEN was suppressed when cells were treated with metformin, a common drug for diabetes, suggesting that PTEN regulates apoptosis in this insulin-resistant muscle model." (PMID 30151071, 2018). "In adipose tissue, liver, pancreatic β-cells and muscle, deletion of Pten consistently lead to enhanced insulin and metabolic sensitivity as well as resistance to HFD induced diabetes." (PMID 30038596, 2018). "Optimising glycaemic control improves clinical status and reduces mortality; insulin therapy is the primary means of controlling glycaemia in CFRD, but its role in managing pre-diabetes is less clear." (PMID 30021636, 2018). "The Diabetes Control and Complications Trial (DCCT) demonstrated intensive insulin therapy reduces retinopathy, neuropathy, and nephropathy in T1DM." (PMID 29652893, 2018). "Treating patients with diabetes of long duration: GLP-1 receptor agonists and insulin in combination." (PMID 29527102, 2018). "Indeed, a cornerstone of current diabetes pharmacotherapy, the sulphonylurea receptor inhibitors (i.e., glibenclamide/glyburide), is aimed at antagonizing the hyperpolarizing IK,ATP current to facilitate β-cell depolarization and thereby potentiate insulin secretion." (PMID 29371604, 2018). "The SIU pocket insulin dosing guide significantly increased the utilization of BBI, decreased SSI orders, and improved hospital glycemic control for patients with diabetes mellitus." (PMID 30155381, 2018). "After nine years of follow-up in the United Kingdom Prospective Diabetes Study (UKPDS), 30% patients had switched to insulin treatment." (PMID 30327785, 2018). "Therefore, we speculate that the increased diabetes risk is attributable to increases in insulin resistance rather than insulin secretion, as has been suggested previously for valine and other BCAAs." (PMID 28936587, 2018). "Third, the observation that low insulin predicted dementia without diabetes comorbidity, and not diabetes mellitus, makes it possible to identify hypoinsulinemia as a risk factor for dementia that is fundamentally different from hyperinsulinemia or diabetes mellitus." (PMID 29997193, 2018). "Compared with women without diabetes, the largest difference in absolute dense volume was found for current use of insulin glargine, whereas for percent dense and absolute nondense volumes, no notable difference in magnitude of association was observed by insulin type." (PMID 30092829, 2018). "Some research suggest SIX3 linkage to diabetes from genetic studies and show SIX3 as possible regulator of insulin production in β-cells in an age-dependent manner." (PMID 30545422, 2018). "Sex, diet, and genotype were all significant variables in both glucose tolerance and insulin sensitivity, suggesting that dysregulation of CRF2 receptor, a key mediator of stress responses, is involved in the development of diabetes and metabolic syndrome." (PMID 30400826, 2018). "The factors which are significantly associated with poor glycemic control were longer duration of diabetes (AOR = 2.72 95%CI:1.16–6.32), and being on insulin therapy (AOR = 3.01 95% CI: 1.5–5.9)." (PMID 29505602, 2018). "Insulin and HOMA-IR levels were higher in females (P < 0.001) than in males with previously diagnosed diabetes and impaired fasting glucose (IFG) and NFG, meanwhile decreased with age (P < 0.001) among IFG and NFG participants." (PMID 30211231, 2018).
diabetes (continued). "Using the identified signatures we explored correlations with other states of metabolic stress including diabetes mellitus and polycystic ovary syndrome and showed that we could recapitulate the malignant phenotype in a murine model by exposing hypoglycemic mice to exogenous insulin." (PMID 30167086, 2018). "The International Operations Hypoglycemia Assessment Tool (IO HAT) study was designed to estimate hypoglycemia in insulin-treated type I (T1DM) and type II (T2DM) diabetes mellitus patients from 9 countries." (PMID 29433560, 2018). "Thus, because it brings together insulin resistance and insufficient secretion of insulin, the multi-transgenic mouse model prepared using the tissue-specific polycistronic system described in this work represents an ideal animal model for pre-diabetes mellitus." (PMID 29682407, 2018). "Insulin measurement showed a significant increase in the diabetes (p < 0.05), diabetes + SLN containing myricitrin, and diabetes + metformin-administered mice (p < 0.001) when compared to the control." (PMID 30116491, 2018). "This study aimed to show similar efficacy, safety, and immunogenicity of SAR-Lis versus Ly-Lis in adult patients with type 2 diabetes mellitus (T2DM) treated with multiple daily injections, while using insulin glargine (GLA-100; Lantus®) as basal insulin." (PMID 29232162, 2018). "The strong direct associations that we found between the genus Collinsella and insulin/HOMA-IR values were in line with studies during pregnancy or not37 showing higher abundance of the lactate-producing Collinsella in type 2 diabetes mellitus." (PMID 30111822, 2018). "Therefore, targeting PTP1B and developing novel PTP1B inhibitors could lead to an effective therapeutic model against diabetes via insulin sensitization, without the weight gain associated with thiazolidinediones." (PMID 29786669, 2018). "Type 2 Diabetes Mellitus (T2DM), a worldwide epidemics, is a progressive disease initially developing an insulin resistant state, with manifest pancreatic beta islet overwork and hyperinsulinemia." (PMID 30386301, 2018). "This study investigated the safety and potential efficacy of continuous subcutaneous insulin infusion (CSII) and continuous glucose monitoring (CGM) in poorly controlled diabetes with gastroparesis." (PMID 29652893, 2018). "For instance, Novo Nordisk offers insulin at a lower price to LMIC countries and several NGOs like Medecines sans Frontieres are including diabetes care in their facilities." (PMID 29670916, 2018). "Insulin and HOMA-IR levels were the highest in newly diagnosed diabetes and were lowest in normal fasting glucose (NFG) (P < 0.001)." (PMID 30211231, 2018). "In animal models of diabetes, inhibition of GRK2 and GRK3 through synthetic peptides rescues glucose tolerance and improves insulin sensitivity." (PMID 30538631, 2018). "The insulin and HOMA-IR levels were the highest in newly diagnosed diabetes participants and were lowest in NFG (P < 0.001)." (PMID 30211231, 2018). "A recent investigation in animals prone to diabetes found that the intake of chia seeds rich in n-3 ALA was able to reduce blood levels of pro-inflammatory cytokines and ameliorate insulin sensitivity." (PMID 30029467, 2018). "Women who develop GDM present a metabolic condition similar to that of type 2 diabetes mellitus (T2DM), characterized by insulin resistance coupled with defective insulin signaling." (PMID 30563117, 2018). "For 2hPG, insulin and HOMA-IR, the increment in probability to develop diabetes is more gradual over the whole range of their corresponding distributions." (PMID 29018885, 2018). "In the present study, adults with a higher dietary GI or GL had less favourable glucose homeostasis, as indicated by higher hepatic insulin resistance (HOMA-IR), higher odds for pre-diabetes, and higher levels of FPG and insulin." (PMID 28341844, 2017).